CD248 (CD248 molecule)
Description:
Cell surface glycoprotein involved in various biological processes including angiogenesis, immune response modulation, and tissue remodeling and repair. Participates in pericyte proliferation through positive modulation of the PDGF receptor signaling pathway. Acts as a scaffold for factor X, triggering allosteric changes and the spatial re-alignment of factor X with the TF-factor VIIa complex, thereby enhancing coagulation activation. Modulates the insulin signaling pathway by interacting with insulin receptor/INSR and by diminishing its capacity to be autophosphorylated in response to insulin. Also regulates LPS-induced inflammatory response in macrophages by favoring the production of proinflammatory cytokines. In human, negatively regulates T-cell proliferation compared with stromal cells where it increases proliferation.
Synonyms: CD164L1; TEM1
Tractability: Antibody: a drug acting on it is in phase 2 or 3 trials; its Gene Ontology location is reachable by antibodies, with high confidence; UniProt predicts a signal peptide or a membrane-spanning region; the Human Protein Atlas places it where antibodies can reach.
Gene: Protein-coding gene on chromosome 11 (66,314,494 to 66,317,044, reverse strand). Ensembl gene ENSG00000174807.
Subcellular location: Membrane
Subcellular location (Human Protein Atlas): Plasma membrane
Gene Ontology:
Molecular function: protein binding; extracellular matrix binding; extracellular matrix protein binding; calcium ion binding
Biological process: cell migration
Cellular component: extracellular exosome; external side of plasma membrane; extracellular matrix; cytoplasm; membrane
Genetic constraint (gnomAD): Loss-of-function variants: 7 observed, 8.05 expected, observed/expected ratio (o/e) 0.87, 90% interval 0.49 to 1.59. That is too few expected variants to judge how well the gene tolerates losing a copy. Missense variants: 912 observed, 980.52 expected, observed/expected ratio (o/e) 0.93, 90% interval 0.88 to 0.98. Synonymous variants: 418 observed, 417.46 expected, observed/expected ratio (o/e) 1, 90% interval 0.92 to 1.09.
Homologues: Orthologues: chimpanzee CD248 (99% identical), macaque CD248 (97% identical), dog CD248 (83% identical), pig CD248 (81% identical), mouse Cd248 (78% identical), rat Cd248 (77% identical), guinea pig CD248 (71% identical), tropical clawed frog cd248 (35% identical), Caenorhabditis elegans T25C12.3 (13% identical), Caenorhabditis elegans ZK1193.2 (12% identical), Caenorhabditis elegans apx-1 (10% identical), Caenorhabditis elegans egas-2 (10% identical), and 4 more. Paralogues in human: CD93 (22% identical), CLEC14A (13% identical), DLL3 (11% identical), CRELD1 (10% identical), DLK2 (9% identical), WIF1 (9% identical), FBLN7 (9% identical), CRELD2 (8% identical).
Diseases named in the same sentence as CD248 in open-access papers:
CD248 is named in the same sentence as 118 diseases in open-access papers, as found by Europe PMC text mining. Sharing a sentence is not in itself a finding about the gene and the disease. The quoted sentences say what the papers report.
sarcoma (27 papers, 2014 to 2025). A usually aggressive malignant neoplasm of the soft tissue or bone. "The endosialin/CD248/TEM1 receptor is expressed on the cell surface of tumor-associated stroma cells as well as in sarcoma and neuroblastoma cells." (PMID 28947977, 2017). "Previously, CD248 was found to be expressed specifically in pericytes, cancer-associated fibroblasts (CAFs), and some tumor cells, such as sarcomas, with very low or limited expression in normal tissue; therefore, CD248 has been considered as a specific target for cancer therapy." (PMID 35317721, 2022). "As for ADCs, antibody-toxin conjugates such as scFv78-Fc-saporin, and hMP-E−8.3-duocarmycin were effective in killing CD248+ sarcoma cells and eradicating sarcoma and osteosarcoma, respectively." (PMID 40276611, 2025). "Plenty of studies have found that CD248 is highly expressed in most kinds of sarcomas, including OS, and CD248 has been found to be related with cell migration and metastasis." (PMID 36997926, 2023). "For example, a phase I trial of MORAb-004, a humanized monoclonal antibody engineered to target CD248, was performed in multiple solid tumor types including pancreatic neuroendocrine, hepatocellular, and sarcoma." (PMID 34869004, 2021). "Near-infrared imaging of tumor-bearing mice was used to validate the selected Fc-fusion protein binding to CD248 expressing sarcoma in vivo." (PMID 30847027, 2019). "In disseminated human sarcoma xenografts, CD248 protein expression was maintained at different anatomic sites." (PMID 30847027, 2019). "CD248 is expressed at high levels by malignant sarcoma cells, by the pericyte component of tumor vasculature and by mesenchymal cells in some fibrotic diseases." (PMID 30847027, 2019). "MORAb-004 (Ontuxizumab), an anti-CD248 humanized monoclonal antibody, is in sarcoma clinical trials." (PMID 30847027, 2019). "Further, CD248 expression was assessed in 86 formalin-fixed, paraffin-embedded human clinical sarcoma specimens." (PMID 30847027, 2019). "CD248 expression was identified in 96% of human sarcomas, of which 81% expressed CD248 both on tumor cells and the tumor vasculature." (PMID 30847027, 2019). "CD248 was demonstrated to be overexpressed in various mesenchymal cells in pathological conditions including sarcomas, inflammation and fibrosis." (PMID 27080864, 2016). "CD248 is expressed not only in different kinds of tumors or cancer such as human carcinomas, sarcomas, and neuroectodermal tumors, but also during physiological processes including corpus luteum formation and wound healing." (PMID 26949398, 2016). "Additionally, CD248 is overexpressed in multiple cancers, such as, breast and skin cancers, neuroblastomas and sarcomas." (PMID 38396325, 2024). "Furthermore, CD248 expression was significantly higher in all high-grade and metastatic sarcomas than low-grade sarcomas, thus CD248 was correlated with sarcoma metastasis." (PMID 36997926, 2023). "Besides its specific expression in tumor stroma (such as CAFs and pericytes) of various tumors, CD248 has been found to be highly expressed in most kinds of sarcomas, including OS." (PMID 36997926, 2023). "Besides, humanized monoclonal antibody ontuxizumab had been developed targeting CD248 and is investigated in clinical trials for colorectal cancer, melanoma and sarcoma." (PMID 35708873, 2022). "CD248 was expressed in sarcoma side population cells, thus, supporting the hypothesis that CD248 is a therapeutic target for sarcoma." (PMID 30847027, 2019). "In sarcoma, CD248 was expressed by malignant cells, perivascular cells, and stromal cells." (PMID 30847027, 2019). "Reliable CD248 PET imaging in sarcoma patients may allow identification of patients that can gain the greatest benefit from anti-CD248 therapy." (PMID 30847027, 2019). "An anti-CD248 immunotoxin may be a promising therapeutic approach for CD248-positive sarcoma including synovial sarcoma, fibrosarcoma, liposarcoma, and osteosarcoma." (PMID 30847027, 2019).
sarcoma (continued). "This initial study provided evidence that CD248 was expressed during development, being a fetal antigen, that it was overexpressed in cancer tissues and that its expression varied between carcinomas and sarcomas." (PMID 30847027, 2019). "All nine sarcoma subtypes tested included specimens with at least 50% immunoreactive tissue components positive with a minimum of 2+ staining intensity, indicating the high prevalence of CD248 in sarcomas." (PMID 30847027, 2019). "CD248 protein was found on sarcoma lines, and neuroblastoma lines." (PMID 30847027, 2019). "Endosialin (Tumor Endothelial Marker-1 (TEM-1), CD248) is primarily expressed on pericytes of tumor-associated microvasculature, tumor-associated stromal cells and directly on tumors of mesenchymal origin, including sarcoma and melanoma." (PMID 27494870, 2016). "CD248 (endosialin; tumour endothelial marker 1) is a C-type lectin-like domain family member highly expressed during embryogenesis, and upregulated on pericytes in vascularised brain tumours and sarcomas." (PMID 25243742, 2014). "Interestingly, the malignant cells of sarcomas proved to be highly positive for CD248 expression." (PMID 27080864, 2016).
lung cancer (12 papers, 2016 to 2025). A malignant neoplasm involving the lung. "CD248, a novel specific marker of myofibroblasts and tumor vessel-associated mural cells, which functions in cell adhesion, migration, and angiogenesis in multiple types of cancer, including lung cancer, melanoma, and renal cell carcinoma." (PMID 39334513, 2024). "It has been reported that CD248 expression is substantially increased on tumor stroma in diverse cancers involving lung carcinoma, breast cancer, hepatocellular carcinoma, melanoma, and so on." (PMID 40276611, 2025). "In fibroblasts specific CD248 gene knock out mice lung cancer model, we demonstrated that CD248 knock out mice diminish the infiltration of M2-polarized macrophages and then inhibit NSCLC cells EMT process." (PMID 38906929, 2024). "CD248 is a possible biomarker for non‐small cell lung cancer (NSCLC)‐derived CAFs, but its role in mediating ECM stiffness to promote NSCLC metastasis is unknown." (PMID 39164826, 2024). "Moreover, CD248 regulates Wnt signaling in pericytes to promote angiogenesis and tumor growth in lung cancer." (PMID 36401329, 2022). "However, recent studies have shown that CD248 promotes angiogenesis in lung cancer." (PMID 40786514, 2025). "In addition, CD248 + mr-CAFs also expressed high levels of angiogenic mediators, participating in angiogenesis, consistent with prior studies that overexpression of CD248 promoted angiogenesis in lung cancer and urothelial carcinoma of the bladder." (PMID 39334513, 2024). "To date, anti-CD248 antibodies such as 3K2L, scFv-1C1m, and scFv-7G22 have been applied to construct CAR-T cells for the therapy of breast cancer, lung cancer, and Ewing sarcoma, respectively." (PMID 40276611, 2025). "CD248-expressing CAFs-derived CXCL12 mediated M2-polarized macrophages and promoted lung cancer progression." (PMID 39759028, 2024). "We found that CD248 is not expressed on pulmonary epithelial cells during TGF-β1-induced epithelial-mesenchymal transition, nor on a lung carcinoma cell line." (PMID 27080864, 2016).
osteosarcoma (12 papers, 2016 to 2025). A usually aggressive malignant bone-forming mesenchymal neoplasm, predominantly affecting adolescents and young adults. "CD248 is highly expressed in ossteosarcoma tissues, and its high expression is associated with lung metastasis; knockdown of CD248 can inhibit the migration and invasion of osteosarcoma cells." (PMID 41382249, 2025). "Elevated CD248 expression levels have been detected in several tumors, such as osteosarcoma and renal cell carcinoma." (PMID 36401329, 2022). "CD248 expression in human MG63 osteosarcoma cells and mouse embryonic fibroblasts produced a pro-proliferative and pro-migratory phenotype." (PMID 30847027, 2019). "The osteosarcoma side population cells had high CD248 and CD133, OCT3/4A, Nanog and Nestin, which are responsible for high self-renewal and deregulated cell proliferation." (PMID 30847027, 2019). "Another ADC against CD248 has been developed conjugated to a DNA‐binding duocarmycin derivative which has shown therapeutic efficacy in a human osteosarcoma xenograft model." (PMID 31287944, 2019). "Upon proliferation, CD248 high osteosarcoma side population cells regenerated the tumor population." (PMID 30847027, 2019). "For example, CD248 expression in osteosarcoma may contribute to cancer invasion and metastasis." (PMID 36401329, 2022).
melanoma (11 papers, 2009 to 2025). A malignant, usually aggressive tumor composed of atypical, neoplastic melanocytes. "We demonstrated the mechanism underlying the cellular autonomous effects of CD248 expression in aggressive phenotypes of melanoma cells associated with tumor metastatic behaviors." (PMID 36401329, 2022). "Loss-of-function approaches in B16F10 melanoma cells were used to study the cell-autonomous effects of CD248 on cell adhesion, migration, proliferation, and vascular mimicry." (PMID 36401329, 2022). "CD248 protein expression is associated with the metastatic melanoma phenotype and promotes tumor progression in the stromal cells." (PMID 36401329, 2022). "CD248 knockdown significantly suppresses tumor growth and metastasis of melanoma and hepatocellular carcinoma in vivo." (PMID 40276611, 2025). "In the same study, more aggressive human melanoma samples exhibited stronger CD248 staining of the myofibroblasts compared to less advanced tumors suggesting that CD248 upregulation is correlated with tumor biology." (PMID 38468017, 2024). "CD248 has been proposed to mediate cell-fibronectin interactions and migration in an exogenous cell model, yet the role of native CD248 in melanoma cell adhesion and migration remains to be investigated." (PMID 36401329, 2022). "The role of CD248 in cell adhesion, proliferation, migration, and VM in melanoma was evaluated using a reductionist approach." (PMID 36401329, 2022). "Knockdown of CD248 in melanoma cells using a specific siRNA markedly reduced CD248 protein expression." (PMID 36401329, 2022). "Thus, we speculated whether CD248 expression is associated with melanoma cell growth." (PMID 36401329, 2022). "Our results indicated that native CD248 expression in melanoma cells promotes cell adhesion, migration, and VM." (PMID 36401329, 2022). "We demonstrated that CD248 expression in melanoma tumor cells is correlated with tumor cell-fibronectin interaction, FAK activation, MMP9 expression, cell migration, and VM." (PMID 36401329, 2022). "Here, we demonstrated that CD248 in melanoma cells also plays an important role in cell adhesion, migration, and VM." (PMID 36401329, 2022). "Taken together, these results indicate that melanoma CD248 plays a vital role in cell-fibronectin interactions and migration." (PMID 36401329, 2022). "In summary, our study demonstrated that melanoma CD248 promotes tumor metastatic behavior by enhancing cell-fibronectin interaction, migration, and VM activity." (PMID 36401329, 2022). "Calculating the acellular area before and after migration revealed that reduced CD248 expression in melanoma cells retarded wound recovery." (PMID 36401329, 2022). "Knockdown of CD248 expression significantly decreased cell adhesion to fibronectin, cell migration, and vascular mimicry in melanoma cells." (PMID 36401329, 2022). "This study aimed to explore the cell-autonomous effects of CD248 in melanoma vascular mimicry to aid cancer therapy development." (PMID 36401329, 2022). "An analysis of CD248 expression in metastatic melanoma specimens was conducted to determine the potential of CD248 as a therapeutic target." (PMID 30847027, 2019). "In human clinical specimens, vascular CD248 staining was observed in neuroblastoma, small cell lung cancer and melanoma." (PMID 30847027, 2019). "Cancers with neuroendocrine properties and/or neuroectodermal origin, including neuroblastoma, small cell lung cancer and melanoma, were assessed for CD248 in human clinical specimens and in human cell lines." (PMID 30847027, 2019). "Furthermore, like CD248 and CLEC14a, anti-gal-1 vaccine has demonstrated promising anti-tumor effects in preclinical melanoma studies, citing enhanced cytotoxic T cell infiltration within tumors." (PMID 38468017, 2024). "We investigated whether CD248 affects melanoma cell migration utilizing two different migration models." (PMID 36401329, 2022).
melanoma (continued). "It has been shown that cancer VM phenotype is inversely associated with melanoma patient survival, whereas there is no report on the survival correlation with CD248 expression level in melanoma patients." (PMID 36401329, 2022). "The cell adhesion assay showed that fibronectin coating promoted cell adhesion, which was strongly inhibited by rCD248D1-4, suggesting that rCD248 may compete for fibronectin binding with melanoma CD248 and impede cell adhesion." (PMID 36401329, 2022). "Thus, CD248 knockdown in melanoma cells inhibited either vertical chemotaxis or horizontal cell migration." (PMID 36401329, 2022). "CD248 has been proposed as a valuable biomarker for evaluating tumor progression in renal cell carcinoma, soft tissue sarcoma, glioblastoma, colorectal cancer, bladder cancer, and melanoma." (PMID 36401329, 2022). "CD248 protein expression has been observed in 70% of melanoma specimens with vessel-like patterns." (PMID 36401329, 2022). "Although we have identified that the lectin domain of CD248 could be the functional region of CD248 that interferes with melanoma VM and metastasis, more specific sequences/regions in the lectin domain might be clearly defined in the future." (PMID 36401329, 2022). "CD248 protein expression in melanoma cells was increased by a fibroblast-conditioned medium." (PMID 36401329, 2022). "Our results show that melanoma CD248 contributes to cell migration and VM in part through modulating cell-ECM adhesion and MMP9 expression, which could promote tumor metastasis." (PMID 36401329, 2022). "Recombinant CD248 (rCD248) proteins were generated, and whether rCD248 interfered with melanoma CD248 functions was evaluated in vitro." (PMID 36401329, 2022). "However, CD248 expression had less of an impact on melanoma cell proliferation." (PMID 36401329, 2022). "Thus, we conclude that melanoma CD248 promotes the malignant transformation of melanoma and could be a therapeutic target for cancer." (PMID 36401329, 2022). "CD248 expression in melanoma cells promotes malignant transformation by increasing the activity of cell adhesion, migration, and vascular mimicry, whereas rCD248 protein functions as a molecular decoy interfering with tumor-promoting effects of CD248 in melanoma cells." (PMID 36401329, 2022). "Moreover, CD248 expression has been detected in 85% of tumor microenvironment vasculature of metastatic melanoma; however, no expression was detected in the normal tissue samples, suggesting that CD248 may contribute to melanoma progression." (PMID 36401329, 2022). "Therefore, we investigated whether CD248 was involved in melanoma VM." (PMID 36401329, 2022). "Melanoma cells adhered to the fibronectin-coated surface in 30 min, but the adhesion and FAK activation were considerably reduced when melanoma CD248 expression was suppressed by siRNA." (PMID 36401329, 2022). "CD248 expression assessment was performed on a tumor microarray with 136 Stage IV and 33 paired Stage III melanoma specimens." (PMID 30847027, 2019). "In cell lines, CD248 was detected in neuroblastoma lines, including cancer stem cell-like side population cells, but was absent in melanoma and was rare and weak in small cell lung cancer." (PMID 30847027, 2019). "The MTT assay using melanoma cells with siCd248 showed that melanoma CD248 expression level might not affect cell proliferation." (PMID 36401329, 2022).